CD44 (CD44 molecule (IN blood group))
Diseases named in the same sentence as CD44 in open-access papers (continued):
Sharing a sentence is not in itself a finding about the gene and the disease.
diabetes (continued). "The diabetes patient (sample 13) and the freshly vaccinated person (sample 15) were cytological abnormal measuring 2 CD44i35 out of 46 CD44+ CRC and 1 CD44i35 out 11 CD44+ CRC, respectively." (PMID 36100762, 2023). "Additionally, regulatory T cells (Tregs) significantly increased in the liver of diabetes vs. non-diabetes (p < 0.01), while CD4+CD44+CD62L− and CD8+CD44+CD62L− effector memory T cells were increased in diabetes with NASH compared to diabetes alone (both p < 0.01)." (PMID 40362271, 2025). "Notably, a CD44 signature has demonstrated efficacy in distinguishing between DKD and diabetes." (PMID 39050866, 2024). "Furthermore, because diabetes is a heritable condition, studying MYCN and CD44 expression in parents and children with a family history of diabetes may offer new avenues for diabetes genetic research." (PMID 37904700, 2023).
lupus (24 papers, 2012 to 2026). "Of note, the analysis of non-TFH CD4 + T helper cells (defined as CD45+ CD19– TCRβ+ CD8α– CD4+ CD44+ CXCR5 – cells) revealed that basophil depletion in lupus-like models impacted only the TH2 cell compartment in both mouse models." (PMID 38649353, 2024). "Therefore, increased surface CD44 expression in DN T cells in Nlrp12–/–/lpr mice may correlate with greater immune activation and the potential mobilization of effector T cells at sites of inflammation in a lupus model driven by the lpr mutation." (PMID 36719379, 2023). "Using a Qa-1 knock in mouse model that impaired CD8+CD44+ICOSL+Foxp3neg Treg activity, it was shown that mice developed a lupus-like autoimmune disorder that was associated with TFH cell dysregulation, increased autoantibodies, and severe glomerulonephritis." (PMID 35493508, 2022). "Accumulation of CD44+ effector T cells and heightened production of IFNγ and IL-17 also play a major role in the development of lupus-like autoimmune disease in EGR2-/-B6 mice." (PMID 35784356, 2022). "In conclusion, a CD8+ Treg (CD44+CD122+Ly49+) population expressing low levels of Helios was detected in lupus-prone genetic backgrounds." (PMID 35784310, 2022). "CD44–HA interaction mediates the recruitment of diverse immune cells, in particular T cells, and contributes to disease activity in lupus." (PMID 33240280, 2020). "It was recently reported that CD74, together with CD44, is upregulated in the kidney and hippocampi of diseased lupus-prone mice and was reduced by treatment with the tolerogenic peptide hCDR1." (PMID 22404985, 2012). "The RhoA/ROCK pathway has been implicated in lupus pathology in a prior study that showed that increased phosphorylation of the ezrin, radixin, moesin (ERM) proteins interact with CD44 to promote the adhesion, migration and inflammatory response of T lymphocytes." (PMID 37790522, 2023). "The inhibition of CD44 suppresses lymphoproliferation in lupus-prone mice." (PMID 35205254, 2022). "The increase of EGR2 in lupus T cells might be a consequence of an inflammatory milieu with heightened T cell activation (CD44+CD4+) following lupus development." (PMID 32646370, 2020). "The increase of EGR2 in CD4+ T cells may reflect the higher rate of activated CD4+ T cells (CD44+CD4+) in lupus mice." (PMID 32646370, 2020). "Moreover, most Tim-3+ CD8 T cells in MRL/lpr lupus-prone mice co-expressed CD44, an activated cell marker, and CD44+ Tim-3+ CD8 T cells decreased significantly in Gal-9-treated mice, suggesting that Gal-9 preferentially decreases Tim-3+ CD8 T cells." (PMID 23585851, 2013). "In the next section, we will discuss the contributing role of HA and CD44 in SLE with particular emphasis of their roles in the progression of lupus nephritis." (PMID 22900150, 2012). "There was a trend for DON reducing the high frequency of W.Yaa effector memory T cells (CD4+CD44+CD62L– Tem), leading to a significantly decreased Tem/CD4+CD44–CD62L+ naive T (Tn) cell ratio, which is typically elevated in lupus-prone mice." (PMID 40956613, 2025). "In lupus-prone MRL-lpr mice, increased CD44 expression was observed in perivascular inflammatory infiltrates, glomerular crescents and cortical tubules." (PMID 39411720, 2024). "In lupus T-cells, ERM proteins show increased levels of phosphorylation along with overexpression of surface molecule CD44 compared to T-cells of healthy controls, promoting T-cell adhesion and TCR-CD3 signaling in lupus patients." (PMID 37215992, 2023). "As the TC lupus-prone model, W.Yaa mice presented an expanded population of CD4+CD44+FOXP3–CXCR5+BCL6+CD162lo/–PD-1+ Tfh cells as well as follicular Tregs (CD4+CD44+FOXP3+CXCR5–BCL6–CD162lo/–PD-1+ Tfr), with a skewed Tfh/Tfr ratio, none of which were altered by DON." (PMID 40956613, 2025).
lupus (continued). "Hyaluronic acid (HA), a component of the extracellular matrix, is the ligand for CD44 and has been implicated in the pathogenesis of kidney inflammation in patients with systemic lupus erythematosus (SLE), but its direct role and mechanism of action have not been studied." (PMID 31572382, 2019). "As we have previously reported in lupus mice, 2DG alone did not reduced the frequency of CD44+CD62−CD4+ effector memory T cells (TEM), and the frequency of these cells did not correlate with joint inflammation." (PMID 30233578, 2018). "We next found that the changes in expression of nine of these twelve adhesion molecules were significantly upregulated on brain-infiltrating CD8+ T cells in TLR7[Tg] lupus-prone mice; namely CD49d, CD11a, CD31, CD54, CD49f, CD29, CD48, and CD43aag, as well as CD44 and CD103." (PMID 28098193, 2017). "In parallel, NSUN4-mediated m5C modification promotes CD8+ T cell exhaustion in systemic lupus erythematosus (SLE) by elevating CD74 expression and activating CD44-mTOR-dependent mitophagy." (PMID 41424859, 2026).
renal carcinoma (24 papers, 2012 to 2025). A carcinoma arising from the epithelium of the renal parenchyma or the renal pelvis. "Conversely, the inhibition of CALCR on renal cancer cell apoptosis was remarkably attenuated by depleting CD44 expression (CALCR + shCD44 group vs. CALCR group, P < 0.001)." (PMID 38985127, 2024). "Collectively, we conclude that spheres and CXCR4+MET+CD44+ cells share a gene signature that distinguishes them from controls and characterizes stem cells in renal carcinoma." (PMID 32066735, 2020). "In the current research, silencing CD44 also can weaken proliferative and invasive abilities of renal cancer cells, which coincided with previous research." (PMID 33287763, 2020). "To answer these questions, we first isolated and cultured human renal cancer stem cells (CD44+/CD105+)." (PMID 30411496, 2019). "Our study found that renal cancer tissues and CD44+/CD105+ HuRCSCs both show high TET1 protein expression." (PMID 30411496, 2019). "At the same time, we found that CD44+/CD105+ renal cancer cells have significantly higher expression of TET1 than CD44‐/CD105‐ renal cancer cells." (PMID 30411496, 2019). "Through flow cytometry, we obtained the CD44+/CD105+ renal cancer stem cell (HuRCSCs) subpopulation." (PMID 30411496, 2019). "Though studies indicate high expression of CD24 and CD44 in renal cancer, more investigations with different experimental approaches are required to examine their importance as CSCs." (PMID 22693526, 2012). "Furthermore, the western blotting was used to investigate CD44 expression after CALCR knockdown in renal cancer cell, and we found that CD44 protein expression was inhibited upon CALCR depletion." (PMID 38985127, 2024). "Notably, CD44 emerged as the only gene consistently showing elevated expression across all three renal cancer types, with statistically significant differences in TCGA-KICH and TCGA-KIRC." (PMID 38985127, 2024). "The aim of the study was to analyze whether the expression of CD44, MMP-2, and MMP-9 in association with the histopathological subtype of RCC affects the survival of patients with renal cancer." (PMID 36831550, 2023). "For example, the glycolysis process was found to be remarkably upregulated in RCC samples, and its core regulatory genes PLOD1, PLOD2, and CD44 could promote the proliferation of renal cancer cells." (PMID 35784919, 2022). "Moreover, three core glycolytic risk genes, CD44, PLOD1 and PLOD2, were capable of promoting the proliferation and invasion of renal cancer cells." (PMID 33287763, 2020). "An increase of CD44 protein was observed in Caki-1 renal cancer cells following hypoxia, which was attributed to the Rho kinase-mediated activation of ERM (Ezrin, Radixin, Moesin) proteins during hypoxia, since ERM proteins are associated with the cytoplasmic domain of CD44." (PMID 22937154, 2012). "Therefore, we selected CD44 as a key target for CALCR in renal cancer progression." (PMID 38985127, 2024). "Therefore, in this research, we answered the question of whether the immunohistochemical expression of CD44, MMP-2, and MMP-9 in association with the histopathological subtype of RCC affects the survival of patients with renal cancer." (PMID 36831550, 2023). "Hence, the aim of this study was to analyse whether the immunohistochemical expression of CD44, MMP-2, and MMP-9 in association with the histopathological subtype of RCC affects the survival of patients with renal cancer." (PMID 36831550, 2023). "have shown that Twist2 is involved in the progression of renal cancer by regulating ITGA6 and CD44 in the ECM-receptor interaction pathway." (PMID 39944833, 2025). "Of the renal carcinoma lines, SN12PM6 cells express more CD44v, while SN12C express more CD44s, with the two TCs expressing equal levels of CD44 overall." (PMID 33637851, 2021). "MTT and Transwell assays revealed that silencing of CD44, PLOD1 and PLOD2 suppressed the proliferation and invasion of renal cancer cells." (PMID 33287763, 2020).
renal carcinoma (continued). "HuRCSCs, identified by the CD44+/CD105+ markers, were found to exhibit significantly higher levels of both genomic 5hmC and TET1 expression compared to non-stem renal cancer cells (HuNRCCs, CD44-/CD105-)." (PMID 41226811, 2025). "Twist2 may promote the migration and invasion of renal cancer cells by regulating the expression of ITGA6 and CD44." (PMID 38254353, 2024). "Immunohistochemistry and immunofluorescence analyses for ClC-5, megalin, cubilin, ANXA3, podocalyxin, CD24, CD44, HSA, and LTA marker were performed on 23 kidney biopsies from patients with Lupus Nephritis and 9 control biopsies (obtained from nephrectomies for renal cancer)." (PMID 37594671, 2023). "Numerous investigators reported the prognostic significance of CD44 overexpression in ccRCC, which is the most common type of renal cancer, but the role of this marker in non-ccRCCs is still not fully understood." (PMID 36079127, 2022). "Therefore, we validated the biofunctions of CD44, PLOD1 and PLOD2 in renal cancer cells through further vitro experiments." (PMID 33287763, 2020). "In addition, FCM results showed that renal cancer cells co‐expressing TET2 and CD44 accounted for 1.82 ± 0.15% of the entire cell population." (PMID 30411496, 2019).
thyroid cancer (24 papers, 2014 to 2025). "This review aims to consolidate current knowledge on the expression of CD44 variants in follicular cell-derived thyroid cancers, with a focus on their implications for MDR." (PMID 40363706, 2025). "A handful of studies have focused on CD44 variant expression in follicular cell-derived thyroid cancers, highlighting its potential as both a diagnostic biomarker and therapeutic target." (PMID 40363706, 2025). "Overexpression of CD44 in thyroid carcinoma is associated with the oncogenic conversion of the ERK signalling pathway." (PMID 27811013, 2016). "Although we analyzed only CD44v6 among the carcinoma-associated variants of CD44, our data suggested the interaction between EpCAM and the other carcinoma-associated variants of CD44 in thyroid cancer as well." (PMID 24727741, 2014). "This is the first report that demonstrates the association of carcinoma-specific complexes comprised of EpCAM with the variant isoforms of CD44 and claudin-7 in thyroid cancer including anaplastic thyroid cancer." (PMID 24727741, 2014). "This review synthesizes existing knowledge on CD44 variant expression in follicular cell-derived thyroid cancers and highlights potential therapeutic strategies to mitigate MDR, particularly in high-burden regions, thereby improving patient outcomes and survival." (PMID 40363706, 2025). "One of the major challenges in studying and targeting CD44 in follicular cell-derived thyroid cancers is its heterogeneity." (PMID 40363706, 2025). "Flow cytometry was employed to assess the expression of putative thyroid cancer stem cell markers CD44 and CD133, as well as ALDH1A1, in MTC cell lines." (PMID 39595993, 2024). "In the case of thyroid cancer cells, CD44 controls cell cycle progression and proliferation via sustaining phosphorylation and activation of the CREB transcription factor." (PMID 35954411, 2022). "Quercetin showed an anti-inflammatory effect via a CD44-dependent interaction with thyroid cancer cells." (PMID 35336985, 2022). "CD44 was recently recognized as a promising marker of TICs in many cancer types, including thyroid cancer." (PMID 24424445, 2014). "Among follicular cell-derived thyroid cancers—including papillary (PTC), follicular (FTC), anaplastic (ATC), and poorly differentiated (PDTC) subtypes—the role of CD44 variants has emerged as a critical factor influencing tumor progression and multidrug resistance (MDR)." (PMID 40363706, 2025). "In thyroid cancer cells, the intracellular protein fragment CD44-ICD released by CD44 proteolytic cleavage translocates to the nucleus, and enhances the binding of transcription factor CREB with the cyclin D1 promoter to promote cyclin D1 transcription and cell proliferation." (PMID 36042265, 2022). "Furthermore, CD44 ICD drives the proliferation of thyroid cancer by increasing cyclin D1 expression and the activity of CREB." (PMID 33804427, 2021). "First, clinostat culture increased the expression of CD44 in thyroid cancer cells." (PMID 30108515, 2018). "Thyroid carcinoma cells harboring activated oncogenes exhibited CD44-ICD accumulation." (PMID 30211160, 2018). "In addition, transfection of FGFR2 into the FGFR2−/low CD44low MKN45 GC cell line resulted in increased CD44 and thyroid cancer protein (TC1), a downstream gene of FGFR2." (PMID 27107424, 2016). "Although several studies demonstrated the association of aggressiveness of thyroid cancer and localization of EpCAM, the involvement of EpCAM in carcinoma-specific complexes with variant isoforms of CD44 and claudin-7 has not been studied in thyroid cancer." (PMID 24727741, 2014). "To reveal the role of LINC00162 and sorafenib treatment in regulating the stemness of thyroid cancer cells, we evaluated the expression of SOX2, NANOG, CD133, and CD44 in B-CPAP cancer cells." (PMID 40804316, 2025).
thyroid cancer (continued). "CD177, a marker of the proinflammatory neutrophil subset, and CD44, which plays an important role in neutrophil adhesion and migration, were upregulated both in UTC and advanced-stage thyroid cancer." (PMID 38719807, 2024). "Expression levels of ALDH1A1, CD44, OCT3/4, and ABCG2 gene were 9.78, 7.02, 9.75, and 7.96 times more in stage III thyroid carcinoma than that in benign thyroid mass, respectively." (PMID 31341476, 2019). "There is an expansion of the CSC population in ATC compared to well-differentiated thyroid cancers with intense expression of the markers CD133, CD44 and nestin." (PMID 29383121, 2017). "CD44, a marker of cancer stem-like cells and epithelial-mesenchymal transition, was found to increase CREB phosphorylation and sustain the proliferation of thyroid cancer cells." (PMID 35528004, 2022). "Thus, in thyroid carcinoma cells, which harbor activated RET/PTC, RAS, or BRAF, CD44-ICD accumulated, a blockade of γ-secretase blunting CD44 processing." (PMID 30211160, 2018).
colorectal tumors (23 papers, 1996 to 2025). "SHK@HA-MPDA achieved tumor-targeted delivery via hyaluronic acid-mediated binding with the tumor-associated CD44, and efficiently arrested colorectal tumor growth." (PMID 37161591, 2023). "CD133 and CD44 are cell membrane markers frequently used to identify cancer stem cells and colorectal tumour-initiating cells." (PMID 38398141, 2024). "CD133+/CD44+ cells phenotype has been reported to exert extensive proliferation, self-renewal, differentiation, and invasion in prostate and colorectal tumors, characteristics that corroborate the CSC phenotype." (PMID 36831395, 2023). "Immunohistochemical staining also showed similar results; patients whose localized colorectal tumors were BRG1-strong had a significantly higher CD44 expression than those with BRG1-moderate tumors." (PMID 35590122, 2022). "CD133 and/or CD44 proteins are important markers for a subset of human colorectal tumor-initiating cells 25-28." (PMID 33994850, 2021). "Despite earlier studies demonstrating that human colorectal tumor-initiating cells are enriched for CD44 or/and CD133 marker proteins 26-28, little is known about how these populations contribute to tumorigenesis." (PMID 33994850, 2021). "Although human colorectal tumor-initiating cells are enriched for CD44+37, CD133+38, or CD44+CD133+ cells 26, 27, little is known about how these subpopulations contribute to tumorigenesis." (PMID 33994850, 2021). "We found that CD44 expression is more common than CD133 expression in human colorectal tumour cell lines and patient samples." (PMID 30899442, 2019). "In this study, for the first time we investigated the expression of CD44 and CD133 in a large panel of human colorectal tumour cell lines and determine association to sensitivity to treatment with anti-HER inhibitors and cytotoxic drugs." (PMID 30899442, 2019). "CD44+/CD24+ populations obtained from colorectal tumors can initiate growth of colonospheres in vitro and colorectal tumors in vivo, and similar cells exhibit TIC activity across a variety of solid tumors." (PMID 30197752, 2018). "The aging-associated genes included significantly many ones that are related to cell cycle progression and ones that contribute to development and progression of colorectal tumors, such as Cd44, Myc and so on." (PMID 27589228, 2016). "Although tumors can arise from ESA+CD44+ALDH− cells taken from the UM-C6, OMP-C5 and OMP-C8 tumor lines, an ALDH+ subset of TG ESA+CD44+ cells does exist in all xenogeneic colorectal tumor lines investigated to date (n = 6)." (PMID 18560594, 2008). "Here we show that xenogeneic colorectal tumors investigated to date contain a subset of TG ESA+CD44+ cells with high ALDH activity, and that this subpopulation is enriched in xenogeneic tumors from mice treated with CPA." (PMID 18560594, 2008). "ESA and CD44 demarcate the subpopulation of cells with tumorigenic ability in all colorectal tumors examined to date." (PMID 18560594, 2008). "The subpopulation of human colorectal tumor cells with an ESA+CD44+ phenotype are uniquely responsible for tumorigenesis and have the capacity to generate heterogeneous tumors in a xenograft setting (i.e. CoCSC)." (PMID 18560594, 2008). "Of note, tumorigenicity is strictly conferred by ESA+CD44+ALDH+ cells in the UM-C4 colorectal tumor line." (PMID 18560594, 2008). "We recently demonstrated that the subpopulation of human colorectal tumor cells with an ESA+CD44+ phenotype is uniquely responsible for generating heterogeneous adenocarcinomas in a xenograft setting." (PMID 18560594, 2008). "Human ESA+CD44+ cells from xenogeneic colorectal tumors can be further subdivided based on CD166 expression, resulting in enrichment for tumorigenic (TG) cells among the CD166+ population." (PMID 18560594, 2008).